RNU6-1242P (RNA, U6 small nuclear 1242, pseudogene)
Gene: Small nuclear RNA gene on chromosome 18 (39,678,520 to 39,678,622, reverse strand). Ensembl gene ENSG00000212354.
Homologues: Orthologues: chimpanzee U6 (100% identical), macaque U6 (83% identical), dog U6 (66% identical), rabbit U6 (65% identical), pig U6 (58% identical), rabbit U6 (58% identical). Paralogues in human: RNU6-80P (75% identical), RNU6-1306P (74% identical), RNU6-21P (74% identical), RNU6-230P (74% identical), RNU6-536P (74% identical), RNU6-672P (74% identical), RNU6-836P (74% identical), RNU6-936P (74% identical), RNU6-1060P (73% identical), RNU6-19P (73% identical), RNU6-207P (73% identical), RNU6-483P (73% identical), and 1286 more.